BRCA2 (BRCA2 DNA repair associated)
Diseases named in the same sentence as BRCA2 in open-access papers (continued):
Sharing a sentence is not in itself a finding about the gene and the disease.
tumor (continued). "The software detected in the tumor tissue the BRCA2 variant c.865A>C p.(Asn289His) (rs766173) not present in the germline DNA with a variant allele frequency (VAF) of 0.013." (PMID 35686104, 2022). "Through sampling these tissues and analyzing their mutation type, it was found that silencing of BRCA2 through methylation was not very common in tumor cells." (PMID 35740092, 2022). "al., detected BRCA2 expression exclusively in the cytoplasm of both normal and GC tumor cells." (PMID 36497436, 2022). "Looking at the average number of BRCA1 and BRCA2 variants detected in the tumor and non-tumor samples, the GeneReader and the Ion S5TM each found on average 11.5 mutations per sample." (PMID 35251494, 2022). "The key proteins in HR, BRCA1, and BRCA2 are two important tumor suppressors." (PMID 35707004, 2022). "IFN-I responses were stimulated in tumor-prone cells of BRCA2 inactivated." (PMID 36618371, 2022). "Lastly, we describe a complex genomic rearrangement affecting BRCA2 at P8, a GG 5 tumor." (PMID 36209207, 2022). "Thirteen PVs were initially detected in tumor-derived DNA, including one case with two BRCA2 PVs." (PMID 35263119, 2022). "BRCA1 and BRCA2 tumour suppressors have key roles in maintaining genome integrity." (PMID 35107878, 2022). "The anti‐tumoral effect of pyridostatin against the BRCA2‐deficient tumours was similar to talazoparib, and neither drug impaired the growth of BRCA2‐proficient tumours." (PMID 35107878, 2022). "However, in the tumor cells where BRCA2 was silenced, methylation silenced BRCA2 by binding to the promoter region and inhibiting other transcription factors from binding, like hypermethylation." (PMID 35740092, 2022). "HMGN4 upregulation in mouse and human cells and the thyroid gland of transgenic mice alters cellular transcriptional profiles, downregulates the expression of the tumor suppressors, including Atm, Atrx, and Brca2, and elevates the level of the DNA damage-marker, γH2AX." (PMID 36568211, 2022). "However, a variety of other mutations exist, especially in tumor suppressor genes, such as CDKN2A, SMAD4, ARID1 or BRCA2." (PMID 36078040, 2022). "Similar findings were reported that NO suppresses the tumor suppressor activity of BRCA2." (PMID 35740092, 2022). "“BRCAness” is used to describe cases in which homologous recombination repair (HRR) defects exist in a tumor in the absence of a germline BRCA1 or BRCA2 mutation." (PMID 35626055, 2022). "Somatic mutations of the tumor-suppressor genes BRCA1 and BRCA2 have also been reported in CCA." (PMID 34312770, 2022). "This is particularly important because, apart from BRCA1/BRCA2 MINAS, other CSG MINAS combinations are rare and so clinicians faced with an individual with non-BRCA1/BRCA2 MINAS will often find it very difficult to predict what the implications are for tumour risks in that individual." (PMID 34983940, 2022). "BRCA2 is a tumor suppressor gene which contributes to homologous recombination." (PMID 35896598, 2022). "The cells with compromised BRCA1 or BRCA2 (BRCA1/2) function accumulate stalled replication forks, which leads to replication‐associated DNA damage and genomic instability, a signature of BRCA1/2‐mutated tumours." (PMID 35107878, 2022). "Future investigation will clarify whether BRCA2-dependent central carbon metabolism reprogramming is relevant to its tumor suppression function." (PMID 35734584, 2022). "Furthermore, genetic inactivation of POLQ is synthetic lethal with HR defects caused by either BRCA1, BRCA2, ATM, RAD51C or FANCD2 defects and tumour overexpression of POLQ correlates with HRD status and a poor clinical outcome." (PMID 35567571, 2022).
tumor (continued). "The nonsense substitution mutation in BRCA2 (c.7285G>T, p.Glu2429X) in tumor M096 has not been described before and is thus not classified in CLINVAR." (PMID 35662281, 2022). "However, BRCA2 isoform usage evolved, with her primary tumor expressing BRCA2-201/Long and recurrences expressing BRCA2-001/Short." (PMID 36344544, 2022). "BRCA1 and BRCA2 are the tumor-suppressor genes in breast cancer." (PMID 35330093, 2022). "In our study, we observed BRCA2-/- in three hyper-deleted tumours from African patients." (PMID 36045381, 2022). "Here we identify the tumor suppressor CDK5RAP3 as a novel BRCA2 helical domain-interacting protein." (PMID 35053516, 2022). "Variants in the CHEK2, BRCA2 and ATM tumor suppressor genes, as well as the ASXL1 and EZH2 Epigenetic Regulators, may support the self-renewal of the proliferating progenitors." (PMID 35896598, 2022). "This panel covers 161 genes, including BRCA1 and BRCA2 as well as several BRCAness genes involved in the repair mechanism, but also other genes, which are frequently altered in solid tumors and can contribute to tumorigenesis and tumor progression." (PMID 35251494, 2022). "The mechanism for a stronger association of a diagnosis of TNBC versus other tumor subtypes with BRCA2 and PALB2 among patients of African and AA ancestry is not obvious." (PMID 33479248, 2021). "TNBC versus other tumor subtype was significantly more frequent among AA patients with pathogenic variants in BRCA2 or PALB2 than among AA cases with no such variants (OR = 2.95 [1.18, 7.37])." (PMID 33479248, 2021). "Ultimately, since they may cooperate in the maintenance of genome stability, definition of the roles of regions throughout BRCA2 with distinct activities, may be necessary to fully understand BRCA2 function as a tumor suppressor." (PMID 34356050, 2021). "Regarding the female dogs, we sequenced 79 BC-related genes, and those with high number of variants shared by tumor fragments and plasma were GATA3 and mTOR (missense), SFRP1 (frameshift insertion), BRCA2 (multi hit), FOXC2, ATM, TGFBR3, and BRIP1 (missense and multi hit mutations)." (PMID 34680380, 2021). "BRCA2 is a DNA double-strand break repair gene and a tumor suppressor." (PMID 33832139, 2021). "BRCA2 exerts its tumor suppressor activity through its role in the maintenance of genomic stability, among which, DNA repair by homologous recombination (HR) and the protection of stalled replication forks from aberrant nucleolytic degradation are well characterized." (PMID 34359619, 2021). "In a tumor scenario, LOH of the wild-type BRCA2 allele may determine whether a patient is a good candidate for PARPi therapy." (PMID 34065235, 2021). "While BRCA2 is broadly recognized to have various roles in DNA damage responses and the maintenance of genome stability, identifying the specific roles of domains throughout BRCA2 is a key to understanding its function as a tumor suppressor." (PMID 34356050, 2021). "The authors proposed that 54 stably expressed (low variable) genes in BRCA2-related tumours may be essential in BRCA2-related tumour viability." (PMID 34287743, 2021). "Except for DNAH2 and BRCA2, all the other genes were shared by the two tumor stages." (PMID 33428592, 2021). "Somatic findings of BRCA2 VUS in a tumor present a similar challenge to germline findings." (PMID 34065235, 2021). "Second, only somatic variants of BRCA1 and BRCA2 were sequenced, while germline mutations were not assayed as only tumor tissues were tested." (PMID 33632156, 2021). "Therefore, BRCA1 and BRCA2-deficient tumor cells are very dependent on PARP for repair, and for this reason, PARPi has a significant effect on DNA damage in such tumor cells, showing great cytotoxicity." (PMID 35095931, 2021). "Intact DDR mechanisms mediated by the BRCA2 gene might hamper the success of induced double-strand breaks, by simply maintaining genomic stability in the tumor cell." (PMID 34298770, 2021).
tumor (continued). "Our findings establish an important function for BRCA2, provide insights into replication fork control during the DNA damage response, and may have implications in tumor suppression and therapy response." (PMID 34645815, 2021). "In contrast, the relationship between a diagnosis of TNBC versus any other tumor subtype and BRCA2 and PALB2 might be different for AA and EA patients." (PMID 33479248, 2021). "BRCA2 is a major tumor suppressor with a critical role in genome integrity maintenance." (PMID 34645815, 2021). "Importantly, while not currently used as a stand-alone method for determining the pathogenicity of variants, functional assays provide a greatly needed tool to aid in the classification of VUS of BRCA2 and related tumor suppressors." (PMID 34356050, 2021). "As BRCA2 functions seem necessary for cellular viability, the specific genetic background that is permissive for tumor growth is unknown." (PMID 34065235, 2021). "In addition, ART558 elicits DNA damage and synthetic lethality in BRCA1- or BRCA2-mutant tumour cells and enhances the effects of a PARP inhibitor." (PMID 34140467, 2021). "BRCA1 and BRCA2 are tumour suppressor genes that code for DNA repair proteins." (PMID 34649841, 2021). "The first stage (TOPARP-A) tested anti-tumor activity of olaparib in a sporadic mCRPC population; the second stage (TOPARP-B) was conducted in patients with known genomic background, specifically BRCA2 or ATM mutations to assess sensitivity to olaparib." (PMID 34575947, 2021). "Using targeted next-generation sequencing analysis of tumor biopsies and germline DNA samples from mCRPC patients one study found that presence of deleterious DDR mutations in BRCA2, ATM, mismatch repair (MMR), and CDK12 genes was more frequent in patients with high tumor membranous PSMA expression." (PMID 34207069, 2021). "However, recent studies have identified new functions of BRCA1 and BRCA2 in the regulation of transcription and RNA processing relevant to their tumor-suppressive activity." (PMID 33593852, 2021). "The tumor suppressor FANCD1/BRCA2 is crucial for DNA homologous recombination repair (HRR)." (PMID 34504103, 2021). "However, understanding BRCA2 function as a tumor suppressor is severely limited by the fact that ~70% of the encoded protein has not been tested or assigned a function in the cellular DNA damage response." (PMID 34356050, 2021). "A total of 232 tumour BRCA1/BRCA2 results were available at the time of analysis from NELCN cases." (PMID 34503154, 2021). "Thus, genetic screens are increasingly being used for the identification of patients and families with LOF germline alterations in BRCA2 and related tumor suppressor genes." (PMID 34356050, 2021). "Therefore, BRCA2 is a classic tumor suppressor gene, similar to related tumor suppressors such as BRCA1 and PALB2, which also function in the cellular response to DNA damage and in the maintenance of genetic/genomic stability." (PMID 34356050, 2021). "Furthermore, NSC617145 treatment led to elevated DNA damage accumulation in BRCA2−/− tumor cells as demonstrated by increased immunohistochemical staining for γH2AX and 53BP1 in tissue sections of BRCA2−/− tumors compared to WT tumors." (PMID 34772932, 2021). "This somatic reversion restored the open reading frame in tumor cells, enabling the synthesis of an in-frame BRCA2 protein and efficient DNA repair through homologous recombination, which is consistent with the resistance to PARP inhibitor treatment this patient experienced." (PMID 33619265, 2021). "The tumor suppressor BRCA2 protects stalled forks from degradation to maintain genome stability." (PMID 34772932, 2021). "Notably, our approach confirmed that the pathogenic BRCA2 variants were fixed within the multiple biopsies and ploidies profiled for each BRCAmut tumor by shared interstitial deletions on chromosome 13 that spanned the BRCA2 locus." (PMID 34011996, 2021). "The inactivation of BRCA1 and/or BRCA2 induces tumor development." (PMID 33915740, 2021).
tumor (continued). "Moreover, T2 tumor size and a histological Grade III have been observed in 3 out of the 6 patients suggesting a severe phenotype for Cis DH BRCA2 mutation carriers." (PMID 34456966, 2021). "Importantly, NSC617145 treatment exhibited >3-fold higher growth inhibitory effect on BRCA2−/− tumor (TGI = 34.70%) as compared to WT tumors (TGI = 10.28%)." (PMID 34772932, 2021). "The single missed HRRm was a BRCA2 insertion (frameshift) mutation detected at 13% VAF in tumour but not observed in baseline plasma." (PMID 34830984, 2021). "This was not the case with the syngeneic BRCA1 mut murine model; the difference in elicited response to ICI is the result of a dissimilar effect in both adaptive and innate immune activation, further proven by direct examination between BRCA1 and BRCA2 mut yielded tumor programs." (PMID 34195090, 2021). "Concordance of BRCA1/BRCA2 PV identified through germline and tumour testing was explored." (PMID 34503154, 2021). "While BRCA1 and BRCA2 are known tumor suppressor genes, they may also function as regulators of cell proliferation and/or cell survival during mouse embryogenesis." (PMID 33854442, 2021). "While there are no recommendations about the timing of BRCA1/BRCA2 mutation analysis concerning pre- and post-therapeutic tumor samples, an adequate collection of tumor samples with a high tumor content prior to surgery is advised." (PMID 32850417, 2020). "For example, PARP inhibitors only kill the BRCA2 fully inactivated tumor cells." (PMID 32980867, 2020). "In addition, BRCA2-related tumours are mainly oestrogen receptor (ER)-positive, and BRCA1-related tumours are mainly ER-negative." (PMID 31948486, 2020). "HT was also demonstrated to be an effective radiosensitizer in BRCA2-deficient tumor cells without active HR, indicating HT-induced blocking of other DNA repair pathways." (PMID 32596144, 2020). "Indeed, the wild-type BRCA2 gene is known as a tumor suppressor gene; BRCA2 maintains genome stability by its involvement in the repair of DNA double-strand breaks (DSBs) during homologous recombination." (PMID 32005245, 2020). "Among the clinically screened patients without a pathogenic germline BRCA1/BRCA2 variant, 16 out of 34 (47.1%) displayed tumor BRCA1 hypermethylation while 18 did not." (PMID 32719340, 2020). "BRCA1 and BRCA2 are tumour suppressor genes located on chromosomes 17 and 13 respectively." (PMID 32022473, 2020). "Interestingly, γ-H2AX was sustained at high levels in all three BRCA2 monoallelic and biallelic mutant tumor cell lines even after MMC removal but returned to baseline phosphorylation status in wild-type SNU-216 cells during the same time frame." (PMID 32980867, 2020). "Considering the frequencies of the variants observed in our study and the limitations of NGS, we recommend performing a specific blood test for the detection of the three most common variants in our population prior to tumor screening of the entire coding regions of BRCA1 and BRCA2 by NGS." (PMID 32850417, 2020). "G4 binders may efficiently target tumours carrying mutations in the DNA damage response, such as BRCA1 and BRCA2." (PMID 32098397, 2020). "BRCA2 deficient mice showed defective cellular proliferation and died in utero Moreover, transfecting Capan-1 cells, which expresses only a COOH-terminal truncated BRCA2 inhibited tumor growth in animal models and negatively regulated cell proliferation." (PMID 33013205, 2020).
tumor (continued). "To verify this hypothesis, we applied genome-scale CRISPR-Cas9 knockout (GeCKO) screening to simultaneously knockout 19050 human genes in SNU-1 cells to explore whether BRCA2 monoallelic mutant tumor cells are selectively targeted by MMC55." (PMID 32980867, 2020). "From these, we selected tumor samples with biallelic loss of BRCA1 or BRCA2, and non-mutated BRCA1/2, to obtain a high confidence set of samples belonging to three classes for classifier training (BRCA1-deficient, BRCA2-deficient, and BRCA1/2-proficient)." (PMID 33149131, 2020). "Second, we showed that Brca2 deficiency alone driven by Villin-Cre was not sufficient to promote gastrointestinal tumor formation but that it robustly elicited tumor formation when genome instability was increased." (PMID 32980867, 2020). "It all began with the discovery of the BRCA1 and BRCA2 tumor suppressor genes." (PMID 31769234, 2020). "Usually, in tumor cells with BRCA1 and BRCA2 mutations or defects, the inhibition of the PARP enzyme can lead to the accumulation of single-strand DNA breaks, owing to the HR repair pathway being blocked, which causes further double-strand DNA breaks and finally results in the death of tumor cells." (PMID 31963730, 2020). "Detection of BRCA2 c.9294C>G mutation in several non-cancerous tissues of this individual excluded circulating tumor cells and clonal hematopoiesis as an origin." (PMID 32468491, 2020). "Tumor BRCA1/2 variant status was determined for 276 patients (251 complete reports with fully sequenced BRCA1 and BRCA2 genes, 25 indeterminate reports with at least one failed exon), of which 17.4% (48/276) had a pathogenic/likely pathogenic variant and 8.3% (23/276) carried a VUS." (PMID 33233347, 2020). "This tumor also had a heterozygous frame-shift variant in BRCA2 that was not covered by a LOH event." (PMID 32873813, 2020). "However, in cases where a lower expression of BRCA2 is observed, what are the mechanisms triggering the tumor development?" (PMID 32005245, 2020). "BRCA2 mutation was more frequently detected than BRCA1 mutation regardless of the location of the tumor in males and accounted for 56.7–100.0% of the cases." (PMID 33054725, 2020). "In this study, we aimed to estimate the prevalence of germline and somatic BRCA1 and BRCA2 variants in a consecutive series of non-mucinous ovarian cancer patients and to evaluate the advantages and limitations of the tumor testing first strategy." (PMID 32850417, 2020). "Furthermore, BRCA1/BRCA2 tumor sequencing allows the detection of both germline and somatic variants in a single test, the latter having a frequency ranging from 4% to 7%." (PMID 33008098, 2020). "In vitro experiments have confirmed that HT, along with a PARP1 inhibitor and CDDP, could boost synthetic lethality even in BRCA2-proficient tumor cells." (PMID 32596144, 2020). "SCYP3 produced outside the meiotic context has been shown to disrupt the activity of the tumour‐suppressing recombination regulator BRCA2 and can modulate the strand invasion capabilities of both the RAD51 and DMC1 (meiosis‐specific) recombinases that drive homologous recombination." (PMID 31102330, 2019). "Interestingly, in this cohort, a high proportion of IDHWT tumours was impacted by BRCA1 (18%) and BRCA2 (18%) mutations." (PMID 32082376, 2019). "Interestingly, Palb2-KPC tumors showed a mixture of Brca1-KPC and Brca2-KPC tumor phenotypes regarding the presence of cysts." (PMID 31877165, 2019). "BCCIP is an important cofactor for BRCA2 in tumour suppression." (PMID 30672100, 2019).